LRG1 (leucine rich alpha-2-glycoprotein 1)
Synonyms: LRG; HMFT1766
Tractability: Small molecule: it belongs to a druggable protein family. Antibody: its Gene Ontology location is reachable by antibodies, with high confidence; UniProt places it where antibodies can reach, with medium confidence; UniProt predicts a signal peptide or a membrane-spanning region.
Gene: Protein-coding gene on chromosome 19 (4,536,402 to 4,540,067, reverse strand). Ensembl gene ENSG00000171236.
Subcellular location: Secreted
Subcellular location (Human Protein Atlas): Vesicles; Predicted to be secreted
Pathways (Reactome):
Immune System: Neutrophil degranulation
Gene Ontology:
Molecular function: protein binding; type I transforming growth factor beta receptor binding; type II transforming growth factor beta receptor binding; transforming growth factor beta receptor binding
Biological process: keratinocyte migration; leukocyte adhesion to vascular endothelial cell; positive regulation of angiogenesis; positive regulation of endothelial cell proliferation; positive regulation of epithelial cell proliferation involved in wound healing; positive regulation of epithelial to mesenchymal transition; positive regulation of keratinocyte proliferation; positive regulation of transforming growth factor beta receptor signaling pathway; wound healing, spreading of epidermal cells
Cellular component: extracellular exosome; extracellular region; ficolin-1-rich granule lumen; membrane; non-collagenous component of interstitial matrix; specific granule lumen; tertiary granule lumen
Genetic constraint (gnomAD): Loss-of-function variants: 1 observed, 1.99 expected, observed/expected ratio (o/e) 0.5, 90% interval 0.17 to 1.75. That is too few expected variants to judge how well the gene tolerates losing a copy. Missense variants: 425 observed, 448.12 expected, observed/expected ratio (o/e) 0.95, 90% interval 0.88 to 1.03. Synonymous variants: 226 observed, 214.69 expected, observed/expected ratio (o/e) 1.05, 90% interval 0.94 to 1.17.
Homologues: Orthologues: chimpanzee LRG1 (99% identical), macaque LRG1 (93% identical), dog LRG1 (73% identical), guinea pig LRG1 (64% identical), mouse Lrg1 (63% identical), rat Lrg1 (59% identical), Drosophila melanogaster CG7509 (23% identical), Drosophila melanogaster CG18095 (23% identical), Caenorhabditis elegans lron-9 (22% identical), Drosophila melanogaster Con (22% identical), Caenorhabditis elegans lron-2 (21% identical), Drosophila melanogaster kek3 (21% identical), and 4 more. Paralogues in human: CHADL (29% identical), CPN2 (29% identical), LRIG1 (26% identical), TRIL (26% identical), LRIG3 (24% identical), LGR4 (23% identical), LGR6 (23% identical), LRIG2 (23% identical), LRRC26 (22% identical), LGR5 (21% identical), LRRTM2 (21% identical), LRRC24 (21% identical), and 10 more.
Diseases named in the same sentence as LRG1 in open-access papers:
LRG1 is named in the same sentence as 248 diseases in open-access papers, as found by Europe PMC text mining. Sharing a sentence is not in itself a finding about the gene and the disease. The quoted sentences say what the papers report.
colorectal cancer (34 papers, 2016 to 2025). A primary or metastatic malignant neoplasm that affects the colon or rectum. "Recently showed that colorectal cancer-associated fibroblasts (CAFs) promote metastasis by upregulating leucine-rich alpha-2-glycoprotein 1 (LRG1)." (PMID 39136000, 2024). "Furthermore, the expression level of LRG1 was associated with the localization and tumor volume of colorectal carcinomas and had predictive value for the early diagnosis and prognosis of colorectal cancer combined with other serum markers." (PMID 35371990, 2022). "Additionally, LRG1 served as a biomarker to detect early high-risk adenomas as well as colorectal cancer." (PMID 35095520, 2021). "STAT3 induced expression of the secreted glycoprotein LRG1 promotes invasion and metastasis in colorectal cancer models, and LRG1 also induces metastasis of melanoma cells via STAT3 activation." (PMID 40597443, 2025). "Similar correlations of high LRG-1 levels in tumor tissue with reduced patient survival were also shown for melanoma, pancreatic and colorectal cancer." (PMID 38413424, 2024). "For example, LRG1 is a cell adhesion molecule whose up-regulation is involved in tumor metastasis, and has recently been shown to be valuable in diagnosis of colorectal cancer and pancreatic cancer." (PMID 38383428, 2024). "LRG-1 was shown to stimulate vascular endothelial growth factor expression in colorectal cancer cells, as well as to activate migration and invasion, both of which are hallmarks of metastasizing cancer cells." (PMID 38413424, 2024). "Although the underlying mechanism is not fully understood, studies in leukemia, pancreatic and colorectal cancer cells describe an anti-apoptotic role of LRG-1 by modulating cell cycle factors and activating tumor-promoting signaling pathways." (PMID 38413424, 2024). "CAFs enhance ovarian cancer invasion and metastasis through DDR2-regulated periostin 27 and promote colorectal cancer metastasis through IL-6-mediated LRG1 upregulation." (PMID 37056933, 2023). "Basic research results suggested that LRG1 promoted the cellular proliferation and apoptosis by modulating runt-related transcription factor 1 expression in colorectal cancer." (PMID 35095520, 2021). "LRG1 with fucosylated triantennary N-glycan were detected as a new combined colorectal cancer marker, which had higher sensitivity exceeding CA19-9." (PMID 35095520, 2021). "LRG1 has been identified to be differentially expressed in colorectal cancer, and a panel of the CEA, IGFBP2, MAPRE1, and LRG1 proteins is potentially a prediagnostic marker in colorectal cancer plasma samples." (PMID 32337221, 2020). "Knockdown of RUNX1 inhibited proliferation and apoptosis induced by Leucine-rich-alpha-2-glycoprotein 1 (LRG1) in colorectal cancer cells." (PMID 31592165, 2019). "What’s more, LRG-1 expression was high in the malignant tissues of patients with colorectal cancer and endometrial carcinoma, and it was correlated with tumor stage and lymph node metastasis." (PMID 30760292, 2019). "What’s more, the knockdown of LRG1 by siRNA resulted in colorectal cancer cell cycle arrest with the accumulation of cells in the G0/G1 phase and reduced the cell numbers in the S and G2/M phases, while stimulation with recombinant LRG1 had an inverse effect." (PMID 28376129, 2017). "LRG1 has been shown to be one of the five plasma proteins that can be used for colorectal cancer (CRC) diagnosis." (PMID 29029535, 2017). "LRG1 levels are elevated in the blood of patients with non-small-cell lung, ovarian, colorectal cancer, and gliomas through TGF-β signaling, which promotes endothelial cell proliferation and angiogenesis." (PMID 29190982, 2017). "The results imply that LRG1 modulates the cell cycle and cell proliferation of colorectal cancer by regulating the expression of cyclin D1, B, and E." (PMID 28376129, 2017).
colorectal cancer (continued). "Our study demonstrated that the silencing of LRG1 expression significantly inhibited the growth of colorectal carcinoma cells; meanwhile, stimulation with recombinant LRG1 enhanced cell proliferation." (PMID 28376129, 2017). "Similarly, PART1 was shown to promote malignant progression of colorectal cancer through the miR-150-5p/LRG1 axis and by sponging miR-150-5p to up-regulate the expression of CTNNB1 and activate Wnt/β-catenin signaling." (PMID 34072264, 2021). "Long noncoding RNA prostate miR-150-5p/LRG1 pathway facilitated the malignant progression of colorectal cancer and might provide a targeted colorectal cancer therapy." (PMID 35095520, 2021). "LRG1 could promote the cellular invasion and growth, which might act as the outcomes of colorectal cancer patients." (PMID 35095520, 2021). "Coincidentally, LRG1 also enhances the EMT via HIF-1α activation in colorectal cancer." (PMID 32982792, 2020). "In addition, LRG1 has been shown to directly induce VEGF-A expression and promote tumor angiogenesis in colorectal cancer cells, while knockdown of LRG1 dramatically reduced VEGF-A expression in mice retina." (PMID 32982792, 2020). "In colorectal cancer cells, LRG1 directly induces VEGF expression and promotes tumor angiogenesis." (PMID 30515388, 2018). "LRG1 has been reported to be up-regulated in several types of carcinomas, but its role in colorectal cancer remains unclear." (PMID 28376129, 2017). "The high plasma and tissue level of LRG1 in CRCs suggests that LRG1 may play role in the tumorigenesis of colorectal cancer." (PMID 28376129, 2017). "However, a multivariate analysis of the test cohort showed that age, TNM stage, tumor location, surgical margin, neural invasion, vascular invasion and also LRG1 expression level were independent prognostic factors of DFS for 312 colorectal cancers." (PMID 29029535, 2017). "Furthermore, the plasma level of LRG1 was remarkably decreased in patients who had resected colorectal cancers, which was consistent with normal patients." (PMID 28376129, 2017). "The results presented above suggest that LRG1 may be involved in the apoptosis of colorectal cancer cells through these classic apoptotic proteins." (PMID 28376129, 2017). "In summary, this is a preliminary study to investigate the role of LRG1 in colorectal cancer." (PMID 26856989, 2016). "For example, LRG1 was upregulated in the serum or plasma of patients with hepatocellular carcinoma, pancreatic cancer, ovarian cancer, lung cancer, and colorectal cancer." (PMID 27378305, 2016). "Whether LRG1 could regulate angiogenesis and be a promising anti-angiogenic therapy target in colorectal cancer were unknown." (PMID 26856989, 2016). "Moreover, activation of the angiogenic factor, LRG1, promotes colorectal cancer progression." (PMID 40927361, 2025). "In addition, analysis of LRG1 expression levels in two integrated phenotypes of colorectal cancer patients which were defined by epithelial or mesenchymal phenotype associated gene signatures indicated that LRG1 was significantly enriched in tumor tissues with EMT status." (PMID 34930899, 2021). "Thus, LRG1 may act as a potential detection biomarker and a new therapeutic target for colorectal cancer." (PMID 28376129, 2017). "However, little is known about the biological function of LRG1 in colorectal cancer." (PMID 26856989, 2016). "We also found that the combination of leucine-rich α-2 glycoprotein 1 (LRG1) and apolipoprotein A4 (APOA4) had the best predictive ability for colorectal cancer and has the potential to be a biomarker." (PMID 38735538, 2024). "log(P/(1-P) = -7.8709 + 4.5956 × IGFBP2 + 0.2732 × ITIH3 + 0.0909 × LRG1 + 0.1015 × C9 -3.2205 × CNDP1 + 0.0239 × ORM1 + 0.0811 × SERPINA1, where P is a value between 0 and 1 that represents the probability of the event (colorectal cancer)." (PMID 38383428, 2024).
colorectal cancer (continued). "Immunoblotting results demonstrated high expression of plasma LRG1 and low expression of APOA4 in colorectal cancer, further validating the results of plasma quantitative proteomics." (PMID 38735538, 2024). "Using a machine learning approach, we determined that the combination of LRG1 and APOA4 serves as the most effective predictive plasma marker for colorectal cancer." (PMID 38735538, 2024). "However, LRG1 from serum samples of pancreatic and colorectal cancer patients shows aberrant glycosylation patterns with regards to content of mannose, fucose and sialic acid suggesting that alterations in sugar chains may influence LRG1 function in cancer." (PMID 35062948, 2022). "Of the remaining inflammatory proteins, those that showed the strongest potential as future colorectal cancer biomarkers were AREG, LRG1 and potentially MIC-1/GDF15." (PMID 34503217, 2021). "In the screening setting, a multi-marker panel containing HP, LRG1 and PON3 had an AUC of 0.65 for detection of advanced adenomas and another panel, optimized for detecting colorectal cancer, reached an AUC of 0.79." (PMID 34503217, 2021). "The plasma level of LRG1 was significantly increased in CRC patients, but it was remarkably decreased in patients with resected colorectal cancers." (PMID 28376129, 2017). "Thus, LRG1 may be a potential biomarker and therapeutic target for colorectal cancer." (PMID 26856989, 2016). "Our results provided evidence for LRG1 function as a novel inducer of EMT and angiogenesis in colorectal cancer, which was at least partially through promotion of HIF-1α expression." (PMID 26856989, 2016). "Our findings identified LRG1 as a novel inducer of EMT and a potential enhancer of the metastatic potential in colorectal cancer." (PMID 26856989, 2016). "Zhang and colleagues found that overexpressed LRG1 could induce the EMT process and angiogenesis in colorectal cancer." (PMID 35794979, 2022). "Leucine-rich-alpha-2-glycoprotein 1 (LRG1) has been reported to be involved in several tumors, whether it participates in colorectal cancer (CRC) progression remains unclear." (PMID 26856989, 2016). "significantly decreased combined indexes of stem cell factor, LRG1, and platelet lymphocyte ratio could be detected in nontreated colorectal cancer patients." (PMID 35095520, 2021). "However, the biological function of LRG1 in the tumourigenesis and progression of colorectal cancer is not yet clear." (PMID 28376129, 2017). "However, the role of LRG1 in colorectal cancer cell apoptosis has not been addressed." (PMID 28376129, 2017).
diabetes (26 papers, 2015 to 2025). "Simulations revealed that LRG1-mediated vascular remodeling in diabetes was associated with lower tissue oxygenation and higher hypoxia susceptibility." (PMID 41124286, 2025). "This is the first study describing a polymorphism risk to LRG1 circulating levels, suggesting a potential use for LRG1 in stratifying patients with diabetes into subsets based on their genetic predisposition." (PMID 38745756, 2024). "For diabetes, several studies have revealed that elevated LRG1 is associated with renal dysfunction in patients with diabetes mellitus." (PMID 38742172, 2024). "Given these biological roles of LRG1, recent studies have investigated the ability of LRG1 to predict the occurrence of cardiovascular events in high-risk populations, such as patients with end-stage renal disease and diabetes." (PMID 38742172, 2024). "In the present study, we found that LRG1 was associated with glycemic status reflected by HbA1c level and diabetes duration, which are important contributors to diabetic kidney injury." (PMID 37916147, 2023). "A longitudinal study of patients with type 2 diabetes mellitus (T2DM) reported that an increased level of plasma LRG1 was associated with albuminuria and chronic kidney disease progression." (PMID 37916147, 2023). "Overall, these previous reports indicate that LRG1 is implicated in the development of diabetes and obesity-related complications in adults." (PMID 35955698, 2022). "LRG1 not only showed relevant mechanisms associated with diabetes but also diabetes-related eye diseases." (PMID 35095520, 2021). "It is therefore important to evaluate the impact of LRG1 on angiogenesis under heart failure-associated disease conditions such as diabetes, hypertension and obesity." (PMID 28509980, 2015). "Additionally, genetically influenced plasma LRG1 levels were also associated with lower cognitive function, further supporting a role for LRG1 as a novel biomarker for cognitive decline in type 2 diabetes mellitus." (PMID 38745756, 2024). "Thus, there remains a need for further investigation of the therapeutic effects of LRG1 on diabetic ED using animal models of ED associated with type 1 and/or 2 diabetes." (PMID 35562586, 2022). "Abnormal levels of LRG1 in the skin of diabetic mice delay the closure of chronic wounds through the formation of NETs, whose dysregulated function is known to cause cell damage in a number of conditions including diabetes." (PMID 35062948, 2022). "Collectively, these findings show that LRG1 expression is upregulated in the retina during diabetes, with hyperglycemia driving this effect in inflamed retinal ECs through NF-κB activation." (PMID 41124286, 2025). "Future studies with larger cohorts will be essential to establish a robust correlation between retinal LRG1 expression, diabetes and DR progression." (PMID 41124286, 2025). "Previous cross-sectional studies have documented elevated LRG1 concentration in plasma and vitreous humor of individuals with diabetes, yet there is limited evidence of LRG1 expression within the retina itself." (PMID 41124286, 2025). "Cross-sectional studies reported LRG1 protein to be increased in plasma and urine of people with diabetes, and proteomic analyses of vitreous humor from patients with DR have revealed that LRG1 is up-regulated." (PMID 41124286, 2025). "Our findings provide the first direct evidence of the presence of LRG1 within the retinal parenchyma of individuals with diabetes." (PMID 41124286, 2025). "Although the involvement of LRG1 has been reported, it is necessary to investigate the interaction between periodontitis and the pathology of periodontal disease‐related diabetes and RA." (PMID 38656694, 2024). "Outside the TGF-β axis, an alternative mechanism has been noted, whereby LRG1 binds to the Latrophilin-2 receptor to promote LRG1-dependent angioneurin effects in diabetes, where angiogenic and neurotrophic processes are in place." (PMID 38745756, 2024).